TG (thyroglobulin)
Diseases named in the same sentence as TG in open-access papers (continued):
Sharing a sentence is not in itself a finding about the gene and the disease.
tumor (continued). "As tumor burden (i.e., primary tumor size and the number of LNM) and tumor extent (i.e., presence of lateral LNM and distant metastasis) increased, we found that preoperative serum thyroglobulin increased." (PMID 32182688, 2020). "The tumor cells were immunoreactive for TTF1, thyroglobulin, thyroperoxidase, CK18, HBME-1, and vimentin." (PMID 32632840, 2020). "However, with the recent trend of choosing lobectomy as a preferred surgical option, preoperative thyroglobulin levels can provide ancillary information about tumor extent before surgery, help to determine the extent of surgery, and flag cases for which a lobectomy may not be sufficient." (PMID 32182688, 2020). "When compared with a metastatic nephroblastoma (Wilms tumor), positivity for thyroglobulin and TTF-1 and only cytoplasmic and very limited positivity for WT1 distinguish this tumor from metastatic Wilms tumor." (PMID 32632840, 2020). "The tumor cells were positive for TTF1, PAX8 and thyroglobulin, and the proliferation indexes were 4% and 1,9% respectively." (PMID 31699114, 2019). "PTC tumours showed underexpression of thyroid function-related proteins TPO, DEHAL1 and thyroglobulin (TG), consistent with the de-differentiation of cellular function." (PMID 27025787, 2016). "In order to destroy residual thyroid gland or microscopic disease, and to allow follow-up with thyroglobulin; RAI ablation therapy is routinely performed in children with gross tumor, extrathyroidal extension, lymph node or distant metastasis." (PMID 26316469, 2015). "The immunohistochemical profile of the current tumor is comparable to previously reported TLFCK cases (AE1/AE3+, CK7+, PAX-2+, PAX-8+, vimentin+, EMA+, TTF-1−, TG−, CD56−, WT-1−, CD10−, and CEA−)." (PMID 25133003, 2014). "On immunohistochemical studies (IHC), tumor cells were positive for calcitonin, TTF-1, and thyroglobulin thus confirming the primary site to be thyroid and the tumor." (PMID 25478248, 2014). "Paired analysis of tumor and corresponding normal thyroid samples (possible in 7 cases) revealed a significant decrease (P < 0.0001) in TPO and TG expression among the tumor group, reinforcing previous results." (PMID 22481925, 2012). "In our case, the resection margin was pathologically negative, no obvious tumor lesions were detected in the orthotopic thyroid gland, and the postoperative thyroglobulin level was normal." (PMID 41250727, 2025). "In our case, the tumor exhibited positive staining for CK5/6, P40, P63, and CK7, while showing negative staining for Napsin A, TTF-1, CD56, Chromogranin A, Synaptophysin, Pax-8, thyroglobulin, and vimentin." (PMID 40061900, 2025). "Serum thyroglobulin levels are usually non-diagnostic in both entities; they tend to be low or normal in ATC due to tumor dedifferentiation and nonspecific in RT." (PMID 41322753, 2025). "Inour case, the tumor cells were negative for thyroglobulin and TTF-1 but positive forPAX8 and HNF1β." (PMID 39700333, 2024). "If the pathologic features of the tumor suggest an intermediate to high recurrence potential, we may administer RAI as adjuvant therapy, even in the presence of a low-post operative thyroglobulin level." (PMID 39272954, 2024). "Three years later, the patient remained asymptomatic and negative for all anatomical tumor evidence and tumor markers (thyroglobulin, TgAb, and CA125)." (PMID 39360691, 2024). "Unlike other types of thyroid cancer, where thyroglobulin is the predominant tumor marker, calcitonin is highly unique to MTC, making it an important diagnostic tool for this subtype." (PMID 38501105, 2024). "Thyroglobulin doubling time also helps the assessment of tumor progression, although the data are not sufficient to use this marker for precise prognostication." (PMID 36765880, 2023). "This tumor is never immunohistochemically positive for markers expressed by all other tumors derived from the follicular epithelial cell like thyroglobulin or PAX8." (PMID 37249797, 2023).
tumor (continued). "Immunohistochemically, tumor cells were negative for thyroid transcription factor-1, negative for thyroglobulin, negative for chromogranin A (positive for normal parathyroid tissue within the nodule), positive for PTH, and positive for parafibromin." (PMID 33978837, 2021). "On immunohistochemistry, all tumor cells were positive for pan cytokeratin and epithelial membrane antigen, but negative for thyroglobulin." (PMID 34941144, 2021). "This infiltrative thyroid tumor shows expression for PAX8 and cytokeratin 19 and can mimic PTC, but the tumor cells are negative for thyroglobulin and show negativity (clone 8G7G3/1) or focal positivity (clone SPT24) for TFF1." (PMID 32632840, 2020). "Subsequently, surgical indications of Hürthle cell tumors are reported as USC ≥ 3, tumor size >4 cm, and thyroglobulin >500 ng/dL (with negative anti-thyroglobulin-antibody)." (PMID 33374707, 2020). "IHC analysis, such as Syn, CgA, CD56, PYY, and thyroglobulin, could also promote the diagnosis of POC, while in our cases, both tumor tissues were positive for Syn, CgA, and CD56." (PMID 33019380, 2020). "Although preoperative thyroglobulin was helpful for predicting tumor burden and extent in DTC, it is not as specific as calcitonin is for predicting MTC." (PMID 32182688, 2020). "Negativity for TTF-1 and thyroglobulin ruled out the possibility that the tumor is of thyroid origin." (PMID 32756201, 2020). "Colonies were cloned from the secondary cultures and analyzed by RT-PCR for mRNA expression of Gp78/AMFR, the tumor stem cell gene markers ABCG2 and Oct-4 and the thyroid differentiation markers thyroglobulin (TG) and thyroid stimulating hormone receptor (TsHR)." (PMID 31431834, 2019). "The tumor cells were positive for cytokeratin MNF116, cytokeratin 7, TTF1, PAX8 and thyroglobulin." (PMID 31699114, 2019). "Unlike serum thyroglobulin measurement or whole-body scans, US can be used to localize a tumor recurrence lesion." (PMID 29764382, 2018). "Immunostaines for RCC, CD10, CK20, chromogranin A, synaptophysin, TTF-1, thyroglobulin, and transthyretin were negative in the tumor cells." (PMID 30340515, 2018). "The TG and TTF1 thyroid differentiation markers are expressed both in tumor and normal spheroids." (PMID 28039458, 2017). "The tumor showed positive immunostaining for Vimentin, CD31, CK7, D2–40, c-MYC, Ki67, focal positivity for PanCK, and negative immunostaining for Factor VIII, CD34, WT1, CK5/6, Calretinin, EMA, HBME-1, CEA, p63, EpCAM, Bcl-2, TTF1 and Thyroglobulin." (PMID 28810922, 2017). "The expression of thyroid differentiation markers, TG (thyroglobulin) and TTF1, was maintained in spheroids and was variable, mostly sparse in spheroids from normal tissues or preferentially located in the peripheral area of tumor spheroids." (PMID 28039458, 2017). "In the case of tumor activity shown by an increasing serum level of thyroglobulin without a macroscopically detectable tumor using morphological and functional imaging RIT can be carried out after carefully weighing risks and benefits." (PMID 28629126, 2017). "Immunohistochemical staining revealed that the large-sized tumor cells were positive for CD20, PAX-5, MUM-1 and BCL-2, and were negative for CD3, CD5, CD43, CD10, CD23, CyclinD1, CD138, CD30, ALK, CD56, MPO, S-100, TTF-1, thyroglobulin and calcitonin." (PMID 28841887, 2017). "Immunohistochemical studies showed positive results for vimentin, actin, and desmin in tumor tissue, whereas other markers including pan-cytokeratin, thyroglobulin, and TTF-1 were negative." (PMID 27080750, 2016). "Immunohistochemically, pan-keratin, thyroglobulin, and S100 were negative in tumor cells, whereas vimentin, desmin, and smooth muscle actin were found to be positive." (PMID 27080750, 2016).
tumor (continued). "Although it is not included as part of guidelines, increased postoperative thyroglobulin levels should warn the clinician for possible lung metastases, unless no residual tumor or metastatic lymph node is present after surgery." (PMID 26316469, 2015). "During follow-up, an additional dose of RAI ablation therapy was administered in five patients because of high thyroglobulin levels (>10 ng/ml) without evidence of tumor recurrence." (PMID 26041024, 2015). "The tumour cells in the present case were immunoreactive to calcitonin, TTF-1, and thyroglobulin." (PMID 25478248, 2014). "The differentiated tumor cells consisted of thyroglobulin-positive and thyroglobulin-negative components, and the undifferentiated tumor cells were negative for thyroglobulin." (PMID 25532447, 2014). "Tumor cells are immunoreactive for epithelial membrane antigen and keratin but are negative for thyroglobulin." (PMID 25214840, 2014). "They reported no staining with thyroglobulin in 90 % of the cases and that, although the remaining 10 % had staining with thyroglobulin, the positive cells accounted for only 1–25 % of the tumor cells." (PMID 24407283, 2014). "Our patient’s tumor was not a metastatic thyroid papillary clear cell carcinoma because there was no tumor found in the thyroid glands and no expression of thyroglobulin." (PMID 24330633, 2013). "In one reported case the tumor was thyroglobulin positive, but the authors did not test TTF-1 or galectin-3." (PMID 23819507, 2013). "The tumor was composed of nests of oval cells with diffusely stippled nuclei staining positive for calcitonin and negative for thyroglobulin." (PMID 23336429, 2013). "Also, in addition to positivity of estrogen, progesteron, cerbB-2, gross cystic disease fluid protein-15 (GCDFP-15) and negativity of thyroglobulin, TTF-1, CEA and calcitonin will make possible the differential diagnosis of tumours originated from the breast." (PMID 22933935, 2011). "Tumor cells were immunoreactive for calcitonin, chromogranin A, and synaptophysin and were negative for thyroglobulin and cytokeratin." (PMID 22185367, 2011). "Complete remissions were defined as negative whole-body scans and negative serum tumor marker thyroglobulin (not higher than the detection limit of 1 ng/mL)." (PMID 24710197, 2011). "However, angiosarcoma tumor cells invariably show immunoreactivity for one or more endothelial markers (factor VIII, CD31, CD34), as well as epithelial markers such as cytokeratins and concomitant negativity for thyroglobulin or podoplanin (D240)." (PMID 40214777, 2025). "However, postoperative pathology of the tumor showed intermingled components, one with negative thyroglobulin but positive calcitonin immunoreactivity consistent with MTC, while the other had the opposite pattern which is consistent with PTC." (PMID 39295705, 2024). "The tumor cells were positive for CA125 andHNF1β but negative for thyroglobulin, TTF-1 and PAX8." (PMID 39700333, 2024). "Immunohistochemically, the tumor cells were positive for paired-box gene 8, thyroid transcription factor-1, and negative for thyroglobulin, calcitonin, and chromogranin A. Inter- and intra-trabecular accumulation of type IV collagen-positive materials was not demonstrated." (PMID 37340328, 2023). "Furthermore, ATCs have confluent areas of tumor necrosis, and the thyroglobulin expression is absent, whereas PDTC are generally characterized by single cells or focal patches of tumor necrosis, and thyroglobulin expression is retained." (PMID 34940089, 2021).
tumor (continued). "As such, cfRNA could be a potential real-time indicator of the residual thyroid tissue volume as opposed to tumour marker, serum thyroglobulin that may take at least 4 weeks for complete thyroglobulin clearance in the absence of metastases." (PMID 34512731, 2021). "Negative thyroglobulin-doubling time indicates tumor shrinkage." (PMID 32733666, 2020). "By immunohistochemistry, the tumor cells are often negative but can be focally positive for thyroglobulin; however, they are positive for TTF1, PAX8 (variable staining intensity), and estrogen and progesterone receptors and are negative for CK20 and calcitonin." (PMID 32632840, 2020). "In addition, the tumor cells were multifocally moderately positive for CD56, scattered moderately positive for S-100, and negative for CD20, PAX8, actin (SM), chromogranin A, synaptophysin, TTF-1, vimentin, and thyroglobulin." (PMID 32756201, 2020). "VA did not decrease tumor size and only generated a modest decrease in serum thyroglobulin levels." (PMID 31540307, 2019). "Moreover, US can detect tumor recurrences in patients with undetectable serum thyroglobulin levels and negative whole body scan." (PMID 29764382, 2018). "The tumor cells were negative for thyroglobulin and showed only focal staining for TTF-1, which often occurs in anaplastic transformation, as studies have demonstrated loss of thyroglobulin and TTF-1 expression in ATC." (PMID 26351607, 2015). "False positive reaction to thyroglobulin may result from nonneoplastic thyroid follicular cells entrapped in the tumor or diffusion from destroyed normal follicles." (PMID 25214840, 2014). "The tumor histology showed spindle-shaped cells arranged in interlacing fascicles that expressed desmine and Hcaldesmone, but were negative for cytokeratins and thyroglobulin." (PMID 23445571, 2013). "Besides, thyroglobulin cannot be considered as a tumor marker in patients whose thyroid gland has not been totally ablated and/or who are positive for the antithyroglobulin antibody." (PMID 22152685, 2011). "Moreover, microchimeric cells negative for either CD45 or thyroglobulin markers were detected in both tumor and normal tissues, suggesting these cells might possess "progenitor-like" properties capable of transdifferentiation into different cell types." (PMID 39945850, 2025). "In these cases, the TAA-AAbs may not only indicate that the results of a tumor marker’s measurements may not be reliable but also provide additional diagnostic information, such as in DTC patients with rising anti-thyroglobulin antibodies (TG-AAbs) (see Section 4.2)." (PMID 35203677, 2022). "Therefore, in this case, the serum thyroglobulin level was not a useful tumor marker." (PMID 24407283, 2014). "At the second instance of thyroglobulin elevation, we speculated that the change in the serum thyroglobulin level observed during external beam radiotherapy was due to collapse of the tumor cells, although no remarkable reductions in the metastatic lesions were noted." (PMID 24407283, 2014). "Finally, the final 14.76% corresponded to subjects that had some biochemical abnormality during follow-up, usually a single elevation of thyroglobulin, but could not be included in the cured group nor in those who had tumor evidence on radiology exams." (PMID 22084734, 2011). "The tumor expresses TTF-1 and peculiarly estrogen and progesterone receptors but is negative for thyroglobulin and either negative or weakly positive for PAX8, suggesting a lack of definitive follicular cell differentiation." (PMID 40111709, 2025). "At immunocytochemistry, the tumor cells were positive for Syn, focally positive for galectin, TTF1, CDX2, thyroglobulin, and negative for Ct and CgA." (PMID 40542625, 2025). "On immunohistochemical (IHC) staining, tumor cells showed patchy expression of CD56, but the tumor was negative for broad-spectrum keratins, PAX8, TTF1, thyroglobulin, calcitonin, HBME-3, CEA, PTH, GATA3, p63, SOX10, and S-100." (PMID 40277780, 2025).
tumor (continued). "Immunohistochemically, the absence of a positive reaction for thyroglobulin and TTF-1 excluded the secondary origin of the tumor from the thyroid." (PMID 40361930, 2025). "When thyroglobulin levels increase in the absence of structurally identifiable disease, patients are classified as having a biochemical incomplete response to therapy and they may elect to receive an ablative or an adjuvant dose of radioactive iodine to facilitate follow-up of their tumor markers." (PMID 39272954, 2024). "In the presented case, there was no doubt about the malignant nature of the tumor; however, the positive expression of PTH and the absence of TTF-1, thyroglobulin, CK7, and HBME-1 expression made it possible to clarify its origin." (PMID 37183888, 2023). "In our first reports on calcitonin DT and thyroglobulin DT, 17% of patients with MTC and 16% of patients with PTC, respectively, had tumor marker DT of negative values." (PMID 36153411, 2023). "In IHC, the tumor cells were positive for TTF-1 and thyroglobulin, but negative for CK19, HBME-1, Galectin-1 and BRAF (V600E)." (PMID 37544981, 2023). "Tumor cells expressed TTF1, PAX8, and p63, NUT protein expression was “equivocal,” and there was no expression of thyroglobulin." (PMID 34997561, 2022). "Only one tumor (0.7% of pRCCs) was found that histologically resembled thyroid parenchyma, despite being TTF1 and thyroglobulin negative, and was diagnosed as TLF RCC." (PMID 34680535, 2021). "Immunohistochemically, tumor cells were negative for thyroid transcription factor-1 (TTF-1), negative for thyroglobulin, negative for chromogranin A (positive for normal parathyroid tissue within the nodule), positive for PTH, and positive for parafibromin." (PMID 33978837, 2021). "The immunohistochemical features of this case were consistent with those of previously reported cases of TL-LGNPPA: the glandular tumor cells exhibited diffuse strong immunoreactivity for TTF-1, but no immunoreactivity for thyroglobulin." (PMID 34941144, 2021). "The IHC analysis of the CASTLE tumor shows a strong positive staining with CD5, p63, and cytokeratin but negative staining with thyroglobulin, TTF1, and calcitonin." (PMID 34399813, 2021). "Immunohistochemical analyses confirmed the tumor as derived from non-thyroidal tissues, as no immunoreactivity was noted for TTF1, PAX8, thyroglobulin, chromogranin A, calcitonin and CEA." (PMID 32519264, 2021). "Patients with high metabolic tumor burden and a negative Rx-WBS scan also had higher thyroglobulin levels and a poorer outcome at final restaging." (PMID 34441364, 2021). "In this case, tumor cells were eosinophilic on hematoxylin and eosin (HE) staining, negative for TTF-1, thyroglobulin, and chromogranin A, and positive for PTH on immunostaining." (PMID 33978837, 2021). "Immunohistochemical staining showed that the tumour cells expressed TTF1, napsin A, and CK7, but not P63, P40, CK5/6, CgA, Syn, CD56, and TG." (PMID 33282636, 2020). "The tumor cells were negative for CK20, synaptophysin, chromogranin A, transthyretin, TTF-1, RCC, thyroglobulin, and CD10." (PMID 30340515, 2018). "Guiping Qin demonstrated that the tumor cells are positive for vimentin, CK, CgA, syn, CEA, calcitonin, HMB-45, and S-100 and negative for TG and TTF-1." (PMID 30424779, 2018). "An Immunohistochemistry showed positive tumor cells with TTF1 and cytokeratin (CK) 7 but negative cells with thyroglobulin and CK20." (PMID 28327204, 2017). "The tumor contained a 3 mm focus of a lesion staining positive for TTF1 and Thyroglobulin, and negative for RCC marker." (PMID 28249616, 2017). "The immunohistochemistry showed positive tumor cells with TTF1 and cytokeratin (CK) 7 but negative tumor cells with thyroglobulin and CK20." (PMID 28327204, 2017). "Immunohistochemistry of the tumor cells revealed positive staining for CEA and negative for thyroglobulin and thyroid transcription factor-1 (TTF-1)." (PMID 23760305, 2013).